KREMEN1 (kringle containing transmembrane protein 1)
Description:
Receptor for Dickkopf proteins. Cooperates with DKK1/2 to inhibit Wnt/beta-catenin signaling by promoting the endocytosis of Wnt receptors LRP5 and LRP6. In the absence of DKK1, potentiates Wnt-beta-catenin signaling by maintaining LRP5 or LRP6 at the cell membrane. Can trigger apoptosis in a Wnt-independent manner and this apoptotic activity is inhibited upon binding of the ligand DKK1. Plays a role in limb development; attenuates Wnt signaling in the developing limb to allow normal limb patterning and can also negatively regulate bone formation. Modulates cell fate decisions in the developing cochlea with an inhibitory role in hair cell fate specification.
Synonyms: KREMEN; KRM1; ECTD13
Tractability: Antibody: UniProt places it where antibodies can reach, with medium confidence; UniProt predicts a signal peptide or a membrane-spanning region; its Gene Ontology location is reachable by antibodies, with medium confidence.
Gene: Protein-coding gene on chromosome 22 (29,072,950 to 29,168,333, forward strand). Ensembl gene ENSG00000183762.
Subcellular location: Cell membrane
Pathways (Reactome):
Signal Transduction: Negative regulation of TCF-dependent signaling by WNT ligand antagonists; TCF dependent signaling in response to WNT
Disease: Signaling by LRP5 mutants
Gene Ontology:
Molecular function: protein binding; transmembrane signaling receptor activity
Biological process: apoptotic process; cell communication; limb development; negative regulation of canonical Wnt signaling pathway; regulation of canonical Wnt signaling pathway; signal transduction; negative regulation of axon regeneration; negative regulation of ossification; Wnt signaling pathway
Cellular component: membrane; plasma membrane; neuronal cell body
Genetic constraint (gnomAD): Loss-of-function variants: 24 observed, 39.8 expected, observed/expected ratio (o/e) 0.6, 90% interval 0.44 to 0.85. The upper end of that interval is the gene's LOEUF score, 0.85, which puts it in group 3 of 6, group 1 being the genes least tolerant of losing a copy. Missense variants: 462 observed, 542.51 expected, observed/expected ratio (o/e) 0.85, 90% interval 0.79 to 0.92. Synonymous variants: 185 observed, 206.56 expected, observed/expected ratio (o/e) 0.9, 90% interval 0.79 to 1.01.
Homologues: Orthologues: macaque KREMEN1 (99% identical), rabbit KREMEN1 (97% identical), pig KREMEN1 (96% identical), guinea pig KREMEN1 (95% identical), mouse Kremen1 (94% identical), rat Kremen1 (93% identical), dog KREMEN1 (93% identical), chimpanzee KREMEN1 (90% identical), tropical clawed frog kremen1 (69% identical), zebrafish kremen1 (57% identical). Paralogues in human: KREMEN2 (38% identical).
Diseases named in the same sentence as KREMEN1 in open-access papers:
KREMEN1 is named in the same sentence as 34 diseases in open-access papers, as found by Europe PMC text mining. Sharing a sentence is not in itself a finding about the gene and the disease. The quoted sentences say what the papers report.
Oligodontia (4 papers, 2016 to 2021). The absence of six or more teeth from the normal series by a failure to develop. "More recently, recessive mutations of KREMEN1 (Kringle Domain-containing Transmembrane Protein 1, OMIM*609898), which encodes another receptor for DKK, were shown to cause a specific form of ectodermal dysplasia (ECTD13, OMIM#617392) that includes oligodontia." (PMID 34834569, 2021).
COVID-19 (2 papers, 2024). A disease caused by infection with severe acute respiratory syndrome coronavirus 2. "We measured the downregulation of KREMEN1 at the onset of COVID-19 in placebo vaccinated individuals compared with ChAdOx1 nCoV-19 recipients." (PMID 38649734, 2024). "Whilst a drop in absolute neutrophil count was observed, cell-specific expression imputed via CIBERSORTx predicted that KREMEN1 was downregulated in the neutrophils of Placebo vaccinated individuals at COVID-19 onset." (PMID 38649734, 2024). "This suggests that the reduction in KREMEN1 observed is due to decreased cellular expression and not solely to a drop in neutrophils during COVID-19." (PMID 38649734, 2024).
foot and mouth disease (2 papers, 2023 to 2025). A viral infectious disease that results in infection in cattle and swine, has material basis in foot-and-mouth disease virus, which is transmitted by contaminated fomites, or transmitted by ingestion of food contaminated with infected meat or animal products. "The KREMEN1 (KRM1) protein is a cellular receptor for multiple enteroviruses that cause hand, foot, and mouth disease (HFMD), including coxsackievirus CVA2, CVA3, CVA4, CVA5, CVA6, CVA10, and CVA12." (PMID 39817751, 2025). "KREMEN1 (KRM1) is the entry receptor for the largest receptor group of hand, foot-and-mouth-disease-causing viruses, which includes CVA2-6, A8, A10, and A12." (PMID 37112912, 2023).
lung carcinoma (2 papers, 2023). "However, the expressions of other receptors (AXL, BSG, KREMEN1, and TFRC) were significantly down-regulated in lung cancer patients." (PMID 38034398, 2023). "Furthermore, Kremen2 is highly expressed in a variety of tumors, particularly in squamous lung cancer, but the expression of Kremen1 is absent in 30 different human tumor cell lines, especially in the human lung cancer cell lines (Lu99, EBC1, SBC2, and SBC5)." (PMID 37270563, 2023).
acne (1 paper, 2024). An inflammatory process of the sebaceous glands which is characterized by comedones, nodules, papules and/or pustules on the skin. "We detected significant enrichment of TSPAN8, along with other novel genes (LGR5, ZNRF3, KREMEN1) and several known acne susceptibility genes, for the GO biological processes gene sets “GO negative regulation of response to stimulus” and “GO regulation of response to stress”." (PMID 36922633, 2024). "Three novel acne associated genes are also involved in the Wnt signaling pathway: ZNRF3 and KREMEN1 from 22q12.1 and LGR5 from 12q21.1." (PMID 36922633, 2024).
diabetes (1 paper, 2023). "For the entry factor of SARS-CoV-2, it was KREMEN1 rather than ACE2 that dominated its myofibroblast elevation, while finally identifying the antifibrotic agent, Nintedanib, as a possible target for diabetes, hypertension, and hypertension-diabetes in SARS-CoV-2 infection-induced fibrotic lungs." (PMID 38144556, 2023).
dysplasia (1 paper, 2023). A usually neoplastic transformation of the cell, associated with altered architectural tissue patterns. "The KREMEN1 gene showed an 18-fold increase in relative expression in tissue with dysplasia when compared to the control." (PMID 37749503, 2023).
hand, foot and mouth disease (1 paper, 2020). A clinical syndrome that is usually caused by enterovirus infection, and that is characterized by fever, anorexia, and painful sores in the mouth, distal extremities, and/or other sites, including the buttocks. "KREMEN1 (KRM1) is the entry receptor for the largest receptor-group of hand-foot-and-mouth disease causing viruses, which includes CV-A10." (PMID 31911601, 2020).
hepatoblastoma (1 paper, 2014). Hepatoblastoma (HB) is a malignant hepatic tumor and is the most common pediatric liver cancer. "We have shown previously that CITED1 repressed epithelial differentiation of cultured metanephric mesenchymes, and induced the WNT inhibitor KREMEN1, the DKK1 receptor, in a hepatoblastoma cell line." (PMID 24481423, 2014).
leukemia (1 paper, 2013). A malignant (clonal) hematologic disorder, involving hematopoietic stem cells and characterized by the presence of primitive or atypical myeloid or lymphoid cells in the bone marrow and the blood. "MN1 and NF2 have previously been implicated in the development of leukemia and solid tumors, and ZNRF3 and KREMEN1 are inhibitors of the Wnt/beta-catenin signaling pathway." (PMID 24236197, 2013).
lung fibrosis (1 paper, 2023). "Taken together, our study reveals that KREMEN1 may be an important alternative receptor in SARS-CoV-2 infection, playing an important role in lung fibrosis and deterioration of lung function." (PMID 38144556, 2023).
myeloma (1 paper, 2010). "The mRNA expression levels of DKK-1 binding receptor LRP5/6 and Kremen1/2 (Krm1/2) were analyzed by Real-time PCR in human myeloma cell line (HMCL) RPMI-8226, NCI-H929, U266, LP-1, CZ-1, KM-3, Sko-007, primary myeloma cells and SCs from 12 MM patients and SCs from 10 healthy donors." (PMID 20846389, 2010).
Osteoblastoma (1 paper, 2013). A rare benign bone-forming neoplasm usually arising from the spine. "Here, we hypothesized that if loss of genes such as ZNRF3 and KREMEN1 and subsequent activation of beta-catenin is important for osteoblastoma development we would find high expression levels of genes activated by Wnt/beta-catenin in these tumors." (PMID 24236197, 2013).
Osteopenia (1 paper, 2021). Osteopenia is a term to define bone density that is not normal but also not as low as osteoporosis. "In the group of patients with osteopenia and without fractures (Group 1), the expression of KREMEN1 (R=−0.672, p = 0.033) negatively correlated with TH T-score and BMD." (PMID 33357212, 2021).
Parkinson disease (1 paper, 2014). A progressive degenerative disorder of the central nervous system characterized by loss of dopamine producing neurons in the substantia nigra and the presence of Lewy bodies in the substantia nigra and locus coeruleus. "Recently, the WNT signaling pathway involving KREMEN1 has been reported to be associated with the cell replacement therapy for Parkinson’s disease." (PMID 25175702, 2014). "KREMEN1 is associated with Wnt signalling pathway which has been shown to play an important role for neurodegeneration in Parkinson’s disease." (PMID 25175702, 2014).
schizophrenia (1 paper, 2013). A major psychotic disorder characterized by abnormalities in the perception or expression of reality. "The involvement in schizophrenia of the KREMEN1 locus appears to be mediated through the rs713526 single nucleotide polymorphism (SNP), which is located in the promoter region of KREMEN1 and showed association with schizophrenia." (PMID 24403877, 2013).
Sepsis (1 paper, 2025). Sepsis is defined as life-threatening organ dysfunction caused by a dysregulated host response to infection. "Conversely, the expression of CCNB2, HJURP, KREMEN1, LILRA5, and SIPA1L2 was significantly higher in the sepsis group (P < 0.05)." (PMID 40129981, 2025).
Stroke (1 paper, 2023). Sudden impairment of blood flow to a part of the brain due to occlusion or rupture of an artery to the brain. "This tile also includes relevant genes that have robust expression in healthy granulocytes or neutrophils, but in stroke are more suppressed in TP3, like KREMEN1, a negative regulator of Wnt/β catenin pathway and PPP4R2, a modulator of neuronal differentiation and survival." (PMID 36803375, 2023).
infection (11 papers, 2018 to 2026). The state of being infected such as from the introduction of a foreign agent such as serum, vaccine, antigenic substance or organism. "According to another recent study, the cell surface molecule KREMEN1 was verified as an entry receptor for CV-A1019, KREMEN1 overexpression enhances CV-A10 binding to the cell surface and increases susceptibility to infection, indicating that KREMEN1 is a rate-limiting factor for CV-A10 infection." (PMID 30190558, 2018). "Recently, it has been shown that KREMEN1 and ASGR1 can mediate entry into cells and that the expression of these two receptors and ACE2 correlates more with susceptibility to infection than either receptor alone." (PMID 38436242, 2024). "Knocking down endogenous hSCARB2 and KREMEN1 with specific siRNAs inhibited CVA10 infection in human cells." (PMID 37112912, 2023). "For CV-A10, KREMEN1 is the dominant receptor used for cell attachment, and uncoating and is a rate-limiting factor for infection." (PMID 37896891, 2023). "CVA10 does not use the common enterovirus 71 (EV71) receptor, human SCARB2 (hSCARB2, scavenger receptor class B, member 2), for infection but instead uses another receptor, such as KREMEN1." (PMID 37112912, 2023). "Co-immunoprecipitation confirmed that VP1, a main capsid protein where virus receptors for attaching to the host cells, could physically interact with hSCARB2 and KREMEN1 during CVA10 infection." (PMID 37112912, 2023). "Cellular molecules, including KREMEN1, ASGR1, and CD147 have been shown to mediate viral uptake, while infection enhancing molecules, such as the phosphatidylserine receptor, facilitate viral internalization in an ACE2-dependent manner." (PMID 35711449, 2022). "It was also noted that over-expression of KREMEN1 in HEK293 cells did not help the infection of r3482 as expected." (PMID 37896891, 2023). "Intriguingly, compared to other host receptors of SARS-CoV-2, such as ACE2, ASGR1, KREMEN1, and TMEM106B exhibits broader and higher expression levels in both cell lines and tissues, implying that TMEM106B may facilitate the infection of ACE2-negative cells in diverse tissues." (PMID 41147188, 2025).
tumor (5 papers, 2019 to 2024). "Somatic mutations in KREMEN1 found in human cancer can affect proapoptotic activity and support tumor suppressive functions." (PMID 36349315, 2022). "It is possible that Kremen2, as a suppressor of Kremen1, inhibits Kremen1-induced cell death and Kremen2 may promote the survival of tumor cells in a ligand-deficient environment." (PMID 37270563, 2023). "Kremen1 was proposed to act as a tumor suppressor, preventing cancer cell survival in a ligand-poor environment." (PMID 31069116, 2019). "Furthermore, in order to investigate epistasis between KREMEN1 and KREMEN2, we compared the influence of KREMEN2 expression on the survival of patients from all cancer cohorts ranked by the level of KREMEN1 expression in tumor." (PMID 31069116, 2019). "In addition, the range of up- or downregulation in tumor versus control tissue was very high compared with KREMEN1 (not illustrated), indicating that Dkk1 is unlikely to damper Krm1 apoptotic activity in all cancers." (PMID 31069116, 2019).
cancer (4 papers, 2019 to 2025). A tumor composed of atypical neoplastic, often pleomorphic cells that invade other tissues. "When considering only the cancer types in which KREMEN1 is upregulated, we found KREMEN2 to fall among the most significantly upregulated genes." (PMID 31069116, 2019). "This was also the case when taking into account only patients that display increased KREMEN1 expression in tumors, regardless of the cancer type." (PMID 31069116, 2019). "Our analysis also revealed ectopic rearrangements affecting multiple known cancer genes, some of which bore the hallmarks of RAG activity (e.g., Ikzf1, Kremen1), while others lacked RSS-like motifs at breakpoint junctions (e.g., Notch1, Pten)." (PMID 31167132, 2019).
KREMEN1 also shares sentences with these, for which no sentence is quoted: ectodermal dysplasia (2 papers); Hypodontia (2); viral infections (2); adrenocortical carcinomas (1); Alzheimer disease (1); aortic valve calcification (1); enterovirus infection (1); epilepsy (1); genetic disorders (1); Hypertension (1); lung squamous cells carcinoma (1); neurological disorders (1); osteosclerosis (1).